EGFR (epidermal growth factor receptor)
Diseases named in the same sentence as EGFR in open-access papers (continued):
Sharing a sentence is not in itself a finding about the gene and the disease.
lung cancer (continued). "Activation of the ERK mitogen-activated protein kinase (MAPK) cascade functions in growth, progression, and survival of human cancers and is linked with EGFR which is involved in HNSCC and lung cancer progression." (PMID 30389917, 2018). "MET, belonging to the RTKs family, is amplified and relevant to the TKIs resistance in EGFR-dependent cancers, especially in lung cancer." (PMID 29455669, 2018). "Ever since the significance of EGFR variations for the clinical response to therapy of lung cancer has been recognized, they have been the subject of intense research around the world." (PMID 30406002, 2018). "EGFR is currently the major therapeutic target in palliative treatment regimens for recurrent and metastatic HNSCCs and colon and lung cancer, with signaling capacities to induce a broad range of cellular outcomes such as proliferation and EMT." (PMID 30261040, 2018). "In this research article, we demonstrated that NEDD4 interacts with EGFR upon EGF stimulation in lung cancer cells." (PMID 29455656, 2018). "Treatment of lung cancer cells with an EGFR-TKI was reported to increase ROS concentrations or Src activation and further induce epithelial-to-mesenchymal transition (EMT)-mediated drug resistance." (PMID 29548337, 2018). "Anti-epidermal growth factor receptor (EGFR) therapy is an effective way to inhibit proliferation of many cancer types such as non–small cell lung cancer (NSCLC) and colorectal cancer." (PMID 30497501, 2018). "We chose this model system because EGFR inhibitors are effective in the treatment of EGFR mutant lung cancer patients, but resistance to these drugs is inevitable." (PMID 29874589, 2018). "It has been reported that AXL is closely relevant to EGFR signaling pathway and mediates the resistance to EGFR inhibition in lung cancer and GBM." (PMID 29843637, 2018). "This study is to elucidate the mechanism by which NEDD4 mediates the EGFR lung cancer migration signaling." (PMID 29455656, 2018). "In this study, the antimigration and anti-invasion properties of propolin C, a biological active compound of Taiwanese propolis, were examined in EGF/EGFR-regulated EMT in lung cancer." (PMID 29681982, 2018). "In contrast to lung cancer patients with EGFR TKD mutations, GBM patients with EGFR ECD mutations have shown disappointing clinical outcomes when treated with the EGFR TKIs, erlotinib and gefitinib." (PMID 29455648, 2018). "In conclusion, our study showed that GNA inhibits lung cancer cell proliferation and tumor growth as a multiple kinase inhibitor, which is probably through the inhibition of cMet, EGFR, and other kinases." (PMID 29449529, 2018). "It is involved in resistance to all the main treatments in lung cancer: cytotoxic chemotherapy, radiotherapy, EGFR TKIs, and possibly to ICIs." (PMID 30235830, 2018). "The role of EGFR in mediating lung cancer pathogenesis is further reinforced by the fact that several histological types of lung cancer respond to therapeutics that inhibit EGFR and/or its downstream effectors." (PMID 30011810, 2018). "Through literature review, we found two DRCEs NOP14‐AS1_hsa‐miR‐335_EGFR and NOP14‐AS1_hsa‐miR‐335_SREBF1 were associated with lung cancer drug responses." (PMID 29464864, 2018). "Small‐molecule EGFR inhibitors (e.g., gefitinib, erlotinib, and afatinib) have been approved for lung cancer treatment as a first‐line therapy in those cases where EGFR mutations have been confirmed." (PMID 29124875, 2018). "Exon 20 insertions are also well described and have been associated with TKI resistance, representing 4–9% of EGFR-mutant lung cancers." (PMID 28988295, 2018). "In this study, we not only demonstrated that SALL4 was highly in lung cancer tissues, but also found that aberrant expression of SALL4 was associated EGFR mutation in NSCLC was essential for the cell stemness of EGFR mutant-driven NSCLC cells." (PMID 29691367, 2018).
lung cancer (continued). "The phase I/II AURA clinical trial enrolled patients with advanced lung cancer that progressed after EGFR-TKI treatment." (PMID 29890761, 2018). "With the emergence of EGFR-TKIs, such as gefitinib, erlotinib, and icotinib, the survival time and life quality of patients with lung cancer have been obviously improved." (PMID 30383772, 2018). "Impaired ubiquitylation and degradation of kinase domain mutants of EGFR were observed in lung cancer cells expressing endogenous EGFR mutants and in other cell systems with exogenous overexpression." (PMID 29976202, 2018). "We wonder if the role of NEDD4 in endosomal trafficking is relevant to the EGFR-promoted lung cancer cell migration." (PMID 29455656, 2018). "For example, MET amplification and HER2 amplification can be detected in EGFR-mutant lung cancers that become resistant to EGFR tyrosine kinase inhibitor therapy." (PMID 29455648, 2018). "Dysregulation of EGF/EGFR signaling pathway is a well-known critical factor of lung cancer tumorigenesis and for the poor prognosis of this cancer." (PMID 29681982, 2018). "After proven effects of osimertinib on CNS metastasis, patients with EGFR‐mutant lung cancer acquire another powerful tool to manage this dismal complication." (PMID 30350450, 2018). "The modified CAR T cells exhibited expansion capability and anticancer efficacy in a time- and antigen-dependent manner in vitro as well as regression of EGFR-positive human lung cancer xenografts in vivo." (PMID 29415996, 2018). "For example, MGL depletion led to induction of EGFR in MGL-deficient MEFs and lung tissues as well as in MGL KD lung cancer cells." (PMID 29348400, 2018). "Taken together, our data have demonstrated that NEDD4 is a key E3 ubiquitin ligase mediating the EGFR cell migration signaling in lung cancer cells." (PMID 29455656, 2018). "Cigarette smoking is one of the leading risks for lung cancer and is associated with the insensitivity of non‐small cell lung cancer (NSCLC) to epidermal growth factor receptor (EGFR) tyrosine kinase inhibitors (TKIs)." (PMID 29570930, 2018). "The identification of activating mutations in the epidermal growth factor receptor (EGFR) has expanded treatment options for non–small cell lung cancer (NSCLC), where the presence of these mutations can sensitize tumors to EGFR inhibitors." (PMID 30588353, 2018). "For example, UCA1 can induce acquired resistance to EGFR-tyrosine kinase inhibitors (TKIs) in EGFR-mutant nonsmall cell lung cancer by activating the AKT/mTOR pathway." (PMID 30377411, 2018). "Our results indicate that SALL4 expression is associated with EGFR mutation and SALL4 inhibition can increase the sensitivity of EGFR TKIs in lung cancer." (PMID 29691367, 2018). "For instance, Tang and Shrager suggested an approach using CRISPR-mediated genome editing in the treatment of epidermal growth factor receptor (EGFR)-mutant lung cancer." (PMID 29592810, 2018). "Non-small cell lung cancers (NSCLC) account for 85% of all lung cancers, and the epidermal growth factor receptor (EGFR) is highly expressed or activated in many NSCLC that permit use of EGFR tyrosine kinase inhibitors (TKIs) as frontline therapies." (PMID 30038713, 2018). "The effects of NUFS‐sErt were similar to those of conventional erlotinib in terms of inhibiting the proliferation of EGFR‐mutant lung cancer cells and suppressing EGFR signaling." (PMID 30350450, 2018). "Between July 2013 and June 2017, 206 patients with pathologically confirmed lung cancer were screened for genetic alterations including HER2 and EGFR mutations." (PMID 29765525, 2018). "The importance of EGFR testing for diagnosis and treatment of lung cancer is illustrated by its worldwide availability." (PMID 29554880, 2018).
lung cancer (continued). "In addition, some researchers supposed that determination of the association between the CT-based radiomic features and the EGFR mutation status could provide a useful clinical predictor in patients with unresectable lung cancer or in whom biopsy was unacceptable." (PMID 30235778, 2018). "Nevertheless, the small proportion of BRAF mutations resulted in negative results (poor prognosis) and provided cognition about mechanisms of acquired resistance to EGFR-TKIs in lung cancer." (PMID 29455669, 2018). "In order to develop effective immune therapy combinations, it is critical to understand tumor immune microenvironment (TME) and identify negative regulators in EGFR-mutant lung cancer for rational design of clinical trials." (PMID 30400822, 2018). "Multiple groups have submitted EGFR mutant lung cancer cell lines to in vitro selection procedures with EGFR-specific TKIs and noted an increase in mesenchymal differentiation in the resulting TKI-resistant cultures." (PMID 29458371, 2018). "In particular, hydroxychloroquine has been used in a lung cancer trial where it was co-administered with the EGFR TKI, erlotinib." (PMID 29937990, 2018). "Epithelial‐mesenchymal transition is another mechanism of acquired EGFR‐TKI resistance in lung cancers." (PMID 29664235, 2018). "Studies have demonstrated that epidermal growth factor receptor (EGFR) is important in lung cancer development." (PMID 29348400, 2018). "Our previous study showed that treatment with miR-140-5p mimic can reduce the invasion properties of lung cancer cells by inhibiting the EGFR signalling pathway." (PMID 30559931, 2018). "A recent study indicates that there are at least three mechanisms by which EGFR activation can promote resistance to therapy targeting oncogenic kinase fusions in lung cancer, including those directed at ALK." (PMID 29455675, 2018). "Short term exposure of human lung cancer cells with EGCG decreased EGF-induced EGFR, AKT and activation of ERK1/2." (PMID 30585192, 2018). "To gain more clinical insights of the effects of combined YAP and EGFR inhibition in lung cancer, we analyzed the effects of statin use in lung cancer patients with EGFR TKI prescription using Taiwan National Health Insurance Research Database." (PMID 29321482, 2018). "Examples include testing for epidermal growth factor receptor (EGFR) to determine the use of erlotinib in advanced nonsmall cell lung cancer (NSCLC), and KRAS testing to determine the use of cetuximab in advanced colorectal cancer." (PMID 29772692, 2018). "Publications focused on the possibility of detecting mutated protein such as EGFR, BRAF... directly on lung cancer tissue by mutation-specific IHC with 92% of sensitivity which is comparable to DNA sequencing." (PMID 30092812, 2018). "Previous studies suggested that the epithelial to mesenchymal transition (EMT) lead to acquired resistance to EGFR TKIs in lung cancer and ESCC." (PMID 30157900, 2018). "For example, ligand/receptor autocrine loops renders EGFR-mutant lung cancer cells less sensitive to EGFR TKI inhibition." (PMID 29455648, 2018). "This review concentrates on various lung cancer biomarkers, including EGFR, ALK, and BRAF, as well as their potential mechanisms of drug resistance." (PMID 29973561, 2018). "Effects of the NEDD4 knockdown on the EGFR-dependent or independent lung cancer cell migration were determined using the wound-healing and transwell assays." (PMID 29455656, 2018). "In the case of lung cancer, it is well known that EGFR or KRAS affects the AKT pathway, whereas wild-type EGFR was reported to be associated with B7-H3 expression." (PMID 30513627, 2018). "A contribution of the HIF-1α/VEGF axis to cisplatin-induced antiangiogenesis was additionally reported for lung cancer cell lines containing exon 19 deletions in the epidermal growth factor receptor (EGFR)." (PMID 30344920, 2018).
lung cancer (continued). "There is a need to identify other molecular biomarkers that can predict the efficacy of EGFR-TKI therapy in patients with lung cancer with wild-type EGFR." (PMID 29970127, 2018). "Cordycepin, a component from Cordyceps sinensis, activated A3 adenosine receptor in bladder cancer cells and inhibited EGFR in lung cancer cells." (PMID 30662512, 2018). "More interestingly, the SALL4 expression in EGFR-mutant lung cancer was significantly higher than that in lung cancer tissue with wild-type EGFR." (PMID 29691367, 2018). "EGFR gene amplification is a frequent phenomenon occurring in many tumors, such as lung cancers, gastric cancer, and breast cancers." (PMID 29849821, 2018). "Flow cytometric analysis validated a high level of EGFR expression on the surface of lung cancer cell lines A549, HCC827, Calu-6, H23, H460, H292, and H1975 but a low level on the H1299 cell surface." (PMID 29415996, 2018). "The MAPK/Erk signaling pathway downstream from EGFR also activates Nrf2-mediated cell proliferation in lung cancer cells." (PMID 30595797, 2018). "According to the analysis of Taiwan’s nationwide lung cancer registry focusing on epidermal growth factor receptor mutation and smoking status, the EGFR mutation rate of younger lung cancer patients was significantly lower than that in the older group." (PMID 29447182, 2018). "Epidermal growth factor receptor‐tyrosine kinase inhibitors (EGFR‐TKIs) have shown some efficacy in patients with CNS metastases from an EGFR‐mutant lung cancer." (PMID 30350450, 2018). "Although patients with EGFR-mutant lung cancer show initial response to TKIs, the benefits of TKI treatments are gradually weakened due to quick development of resistance by tumors." (PMID 29875309, 2018). "SNX1 is also reported to suppress EGFR membrane recycling and activate EGFR/PI3K/AKT signaling pathway in lung cancer cells." (PMID 29868263, 2018). "Recently, epidermal growth factor receptor (EGFR) was a key molecule in investigation of lung cancer, and it was a target for a new therapeutic strategy, based on molecular analyses." (PMID 30406002, 2018). "For instance, the epidermal growth factor receptor (EGFR) represents currently a major target in lung cancer therapy." (PMID 30483474, 2018). "The epidermal growth factor receptor (EGFR) and further activation of its downstream pathways lead to cell proliferation, especially in lung cancer." (PMID 30176876, 2018). "Epidermal growth factor receptor–tyrosine kinase inhibitor (EGFR-TKI) resistance is one of the most important problems in lung cancer therapy." (PMID 29463039, 2018). "Analysis of a larger set of samples is predicted to shed considerable light on the heterogeneity of the reprogramming response in residual EGFR mutant lung cancer." (PMID 29458371, 2018). "MET amplification is a mechanism of resistance to epidermal growth factor receptor-targeted tyrosine kinase inhibitors (EGFR-TKIs) in lung cancer." (PMID 30469509, 2018). "The present meta-analysis showed that SUVmax cannot be used as a surrogate marker for EGFR expression in lung cancer." (PMID 29983647, 2018). "In this study, we reported that miR‐1‐3p and miR‐206 can overcome HGF‐induced gefitinib resistance in EGFR mutant lung cancer cells in vitro and in vivo, and the mechanisms were related to inhibit Akt/Erk pathways and meanwhile suppress HGF‐induced EMT." (PMID 29664235, 2018). "Together, these data suggest that ERK activation plays a vital role in mediating the inhibitory effects of BCI treatment in KRAS or EGFR mutant lung cancer cells." (PMID 30475204, 2018). "In present studies, the anti-migration and anti-invasion activities of propolin C in EGF/EGFR-mediated EMT in lung cancer cells were examined." (PMID 29681982, 2018). "Second-generation irreversible EGFR-TKIs such as afatinib are effective in untreated EGFR-mutant lung cancer." (PMID 29879078, 2018).
lung cancer (continued). "Eventually, a potential synergism of action was demonstrated in combination with anti-EGFR in studies in vitro using lung cancer cell lines such as A 549, H-292." (PMID 30225260, 2018). "Our study for the first time indicated the new function of miR‐1‐3p and miR‐206 in overcoming HGF‐induced gefitinib resistance in EGFR mutant lung cancer cell." (PMID 29664235, 2018). "Serum/plasma from EGFR-mutant lung cancer patients with T790M-AR was collected before and during osimertinib treatment." (PMID 29930751, 2018). "Epidermal growth factor receptor (EGFR) plays a crucial role in human non–small cell lung cancer (NSCLC) tumorigenesis." (PMID 29239135, 2018). "In this report, we found that NEDD4 interacts with EGFR and participates in both the basal and the EGFR-signaling-dependent lung cancer cell migration." (PMID 29455656, 2018). "Studies using EGFR-mutant lung cancer models showed that EZH2 inhibition increases the sensitivity to topoisomerase II G12D/adenocarcinomas." (PMID 30060526, 2018). "Previous studies have shown a relatively high frequency of co-expression of EGFR and NGcGM3 antigen in several human tumors, i.e particularly on lung cancer patients more than 50% of the tumors are double positive." (PMID 29844873, 2018). "A functional genomic screen identified YAP1 as a key determinant that conferred resistance to EGFR-TKI in lung cancer cells." (PMID 29435131, 2018). "The discovery of mutations in the epidermal growth factor receptor (EGFR), as well as that of EGFR-tyrosine kinase inhibitors (TKIs), introduced a new era of precision medicine in lung cancer treatment." (PMID 29643378, 2018). "EGFR-targeted therapy represents one of the most successful approaches in the treatment of lung cancer, which has been approved by the FDA as first-line therapy that effectively prolonged patient survival." (PMID 29976202, 2018). "Comparing with EGFR wild type, longer progression-free survival (PFS) and higher objective radiographic response rates were also observed in patients with mutated EGFR lung cancer." (PMID 30547844, 2018). "In summary, we demonstrated in vitro and in vivo that miR‐1‐3p and miR‐206 can restore HGF‐induced gefitinib resistance in EGFR activating lung cancer cells." (PMID 29664235, 2018). "In our investigation of 2011–2012 claims, we treated code 83912 in the combination with diagnosis codes for lung cancer as a proxy for EGFR/KRAS testing, but this type of analysis can only yield approximate numbers." (PMID 29554880, 2018). "In conclusion, inhibition of migration and invasion via propolin C was suggested by the inhibition of EGFR-mediated signaling pathway in lung cancer cells." (PMID 29681982, 2018). "For example, the receptor tyrosine kinase (RTK), epidermal growth factor receptor (EGFR), is frequently mutated in lung cancer, activating the Ras/ERK pathway and driving cell proliferation." (PMID 29732370, 2018). "And the complex restored the activation of PI3K/Akt pathway driving the TKI resistance and contributing to the carcinogenesis, proliferation, and metastasis in EGFR-mutant lung cancer." (PMID 29455669, 2018). "Considering the critical roles of EGFR in lung cancer tumorigenesis and drug resistance, the thorough investigation of its features in lung cancer is prerequisite for the development of novel therapeutic strategies in the treatment of lung cancer." (PMID 29976202, 2018). "This problem is particularly evident in lung cancer, in which, despite the advances in therapeutic options such as EGFR‐TKIs, mortality rate still remains among the highest of cancer‐related deaths." (PMID 29449326, 2018). "Genetic changes of other genes have been identified, but EGFR, ALK and KRAS mutations are the most frequent mutations in lung cancer." (PMID 30680072, 2018). "Specifically, the integrin subunit β1 is reported to regulate signals downstream of the EGFR in breast and lung cancers, and is a putative drug target in several solid tumors." (PMID 29515334, 2018).